INS (insulin)
Diseases named in the same sentence as INS in open-access papers (continued):
Sharing a sentence is not in itself a finding about the gene and the disease.
COVID-19 (continued). "The study’s focus on investigating the role of Faecalibacterium in modulating insulin resistance and coagulation within the context of LC represents a novel and highly relevant contribution, especially considering the ongoing global health challenges posed by COVID-19 and its long-term effects." (PMID 39081294, 2024). "Kaplan–Meier curves showed that a higher risk of all-cause mortality in patients with COVID-19 and T2DM might be caused by the inhospital use of insulin; however, the use of metformin and AGIs performed a lower risk (p < 0.001), consistent with our above results." (PMID 38755442, 2024). "Furthermore, the accumulation of angiotensin II in COVID-19 may affect pancreatic homeostasis, contributing to insulin resistance, hypoxia, and extracellular acidification via pancreatic Na+/H+ exchanger activation." (PMID 38397885, 2024). "Since the beginning of the pandemic, clinicians and researchers have been scared that SGLT-2 inhibitors, GLP-1 receptor agonists, pioglitazone, and insulin might lead to overexpression of ACE-2 receptor and thus cause more SARS-Cov-2 infections and worse COVID-19 outcomes." (PMID 38538694, 2024). "Whether the COVID-19 virus affects the pancreas to cause absolute insulin deficiency or works by mechanisms to increase insulin resistance at the cellular level is not proven by the currently available literature." (PMID 38192935, 2023). "Care must be exerted while recommending most commonly prescribed anti-diabetic drugs such as biguanides, SGLT2 inhibitors, DPP-4 inhibitors, sulfonylureas, and insulin as recent reports have observed that these drugs might exacerbate clinical conditions in COVID-19 cases." (PMID 36839456, 2023). "Among medical help-seeking posts, in addition to the demand for COVID-19 related medical assistance, people also urgently seek help for the treatment of other diseases, especially those that require long-term treatment or have a strong dependence (e.g., hemodialysis and insulin)." (PMID 37076879, 2023). "Indeed, cytokine storm, commonly found in COVID-19, may impair β-cell insulin secretion and glucose control." (PMID 37629291, 2023). "The evidence was strengthened that male sex, older age, blood glucose level at admission, use of insulin, use of metformin (inversely), lymphocyte count at admission (inversely) and pre-existing comorbidities such as CVD, CKD and COPD are associated with worse COVID-19-related outcomes." (PMID 37204441, 2023). "These COVID-19-related containment measurements led to increased HbA1c concentrations and poor glycemic control, which might also explain the increasing rates of insulin use among mothers with GDM during the SARS-CoV2 pandemic." (PMID 36079820, 2022). "However, although essential, it is unclear whether higher levels of blood insulin are beneficial for patients with COVID-19, and if such levels result in lower inflammatory markers." (PMID 35530861, 2022). "Having proved an association between the surface IDE levels and the metabolic perturbations in the PBMCs from COVID-19 and post-COVID-19 patients, we sought to investigate whether insulin and glucose could directly modulate IDE expression on circulating human PBMCs." (PMID 36232381, 2022). "The pro-inflammatory state of COVID-19 could explain this and the disturbance of the Angiotensin 1-7 counter-regulation of Angiotensin 2, leading to a higher degree of insulin resistance and possibly the accompanying organ damage involving the pancreatic islet cells." (PMID 35274050, 2022). "Studies suggesting an extensive amount of entry factors in β-cells not only identify SARS-CoV-2 nucleocapsid protein in COVID-19 pancreatic tissues but show that human islets could be infected with SARS-CoV-2 ex vivo to disorganize insulin homeostasis and provoke β-cell apoptosis." (PMID 36992767, 2022).
COVID-19 (continued). "Both patients with acute COVID-19 and those recovering from COVID-19 were found to have an increased insulin response to arginine stimulation compared with healthy individuals, which suggested that COVID-19 may cause β-cell hypersecretion, which could, in turn, result in relative secretory failure." (PMID 36569723, 2022). "Additionally, we raised an interesting and significant question regarding the mechanism underlying the relationship between insulin and the development of COVID-19, as there are no reasonable explanations." (PMID 34367067, 2021). "Therefore, we speculate that insulin treatment may participate in the development of COVID-19 by promoting proinflammatory system to aggravate inflammation disorder and pulmonary disease." (PMID 34367067, 2021). "Therefore, increased severity of COVID-19 after insulin administration may be partly attributed to the ACE2 receptor." (PMID 34867819, 2021). "To verify whether insulin is independently associated with increased COVID-19-related mortality we screened the English literature for studies reporting SARS-CoV-2 infection and/or COVID-19-related mortality in insulin users." (PMID 34173070, 2021). "However, whether insulin injection has some effect on the development of COVID-19 remains inconsistent." (PMID 34367067, 2021). "In patients with a severe course of COVID-19, viral-induced inflammation may affect the functions of the skeletal muscle and liver, which are the major organs responsible for insulin-mediated glucose uptake, thereby increasing insulin resistance." (PMID 34299225, 2021). "Intensified insulin dosing along with more frequent BG monitoring or potentially using continuous glucose monitoring devices varied from non-COVID-19 patients could assist in maintaining adequate time in the range of blood glucose level (70–150 mg/dL) and thus, improve ICU outcomes." (PMID 33198177, 2020). "Moreover, an observational study revealed significantly higher insulin requirements among COVID-19 patients, which might be attributed to the beta-cell dysfunction induced by SARS-CoV2." (PMID 33584268, 2020). "Therefore, we must always keep in mind that there could be a dark side of COVID-19 towards the insulin–glucose axis given its role in acutely infecting the liver and β-cells at a molecular level." (PMID 32438687, 2020). "Patients with COVID-19 frequently develop reduced insulin sensitivity due to SARS-CoV-2–induced β-cell damage, often necessitating increased insulin dosages, particularly during febrile episodes when metabolic demand is heightened." (PMID 40564201, 2025). "The increasing absorption band at 1743 cm−1, corresponding to vCHO aldehyde groups, strongly supports the suggestion that lipid hydroperoxidation most likely occurred due to oxidative stress from COVID-19 in TZD- and insulin-medicated patients." (PMID 40650107, 2025). "In clinical studies, both adiponectin levels and adiponectin-to-leptin ratios, widely used as insulin sensitivity indicators in T2DM, are significantly reduced in COVID-19 patients." (PMID 40564201, 2025). "For example, in an organ-specific manner (ovary, pancreas, and thyroid), downregulation of endocrine-specific genes such as IAPP, HSD3B2, INS, LEP, FOXE1, TSHR, and CRYGD has been identified in COVID-19 patients." (PMID 41488148, 2025). "The renal cell carcinoma, neurotrophin, and HTLV-1 pathways affect the symptom of COVID-19 in aspect of regulation of pro-inflammatory cytokines, and the TCA and insulin pathways affect through host metabolic inhibition." (PMID 41139925, 2025). "Through additional subgroup analyses by insulin and ARB use, we aimed to refine our understanding of the potential mortality-reducing effects of DPP-4 inhibitors in diabetic patients with COVID-19." (PMID 40869643, 2025). "The increased incidence was primarily driven by greater pre-existing insulin usage and SARS-CoV-2 infection in the COVID-19 positive cohort." (PMID 40804810, 2025).
COVID-19 (continued). "By double immunohistochemical staining of insulin (AP-red) and glucagon (DAB-brown), the lesions in the islets of the elder COVID-19 models were clearly shown." (PMID 38609366, 2024). "Recent evidence showed that the risk of newly diagnosed DM increased after COVID-19 infection, and one-third of patients who had recovered from COVID-19 exhibited elevated glucose indices marked by an increase in HOMA-IR, FBG, and insulin levels." (PMID 39062154, 2024). "Predictors of COVID-19 hospitalisation in PWDM were age per 5-year ageing interval (OR 1.15, 95% CI: 1.13, 1.17), being male (OR 1.41, 95% CI: 1.29, 1.54), and insulin treatment (OR:1.39, 95% CI:1.24, 1.57)." (PMID 38976666, 2024). "Among 5029 patients admitted over eight months (February 2020 to September 2020) with DKA in the US, managed using the computerized insulin infusion protocol (CII), 4% had COVID-19 disease." (PMID 39060948, 2024). "As for adiponectin, resistin, and insulin, their concentrations showed an increase; a decrease in GLP-1, leptin, and PYY was also reported in the colostrum of mothers suffering from COVID-19 compared with the control group." (PMID 38610889, 2024). "With regard to colostrum, adiponectin, resistin, and insulin concentrations showed an increase, while a decrease in GLP-1, leptin, and PYY was also reported in the colostrum of mothers suffering from COVID-19 compared with the control group." (PMID 38610889, 2024). "As an indication of a systemic response to COVID-19, we found enrichment of the same signaling pathways in multiple cell types and across organs, including HIF-1, insulin, and Notch signaling." (PMID 37830426, 2023). "Endocrine-specific genes (e.g., HSD3B2, INS, IAPP, TSHR, FOXE1, LEP, and CRYGD) were deregulated in COVID-19 cases in an organ-specific manner." (PMID 37246981, 2023). "In combination with the variability of some of the insulin treatment characteristic secondary outcomes, it further shows how the management of DKA in COVID-19 patients can vary." (PMID 36741601, 2023). "The second meta-analysis showed instead that treatment with metformin (OR 0.74), DPP-4is (OR 0.88), SGLT-2is (OR 0.82), and GLP-1 RAs (OR 0.91) was related to reduced COVID-19 mortality rates in T2DM subjects, while insulin to increased mortality." (PMID 37626788, 2023). "Importantly, it allowed us to discriminate the metabolic abnormalities associated with fatal COVID-19 and to complement the NMR data, providing insightful information regarding the alterations in one-carbon metabolism and in metabolites associated with insulin sensitivity and inflammation." (PMID 37512587, 2023). "Mild COVID-19 induces a pro-inflammatory response with higher amounts of inflammatory cytokines, and inducible protein-10 (IP10) expression, which leads to lesser insulin sensitivity." (PMID 36839456, 2023). "(2021) demonstrated in cadavers that 70% of the COVID-19 patients have vasculature ACE2 expression, but just 30% showed ACE2-expression in insulin-producing islet cells." (PMID 36992767, 2022). "In the present study, IR was increased while insulin sensitivity and pancreatic β-cell function were distorted in T2DM patients with COVID-19 at the time of admission." (PMID 36355535, 2022). "Treatment with insulin leads to optimal glycemia control in patients with T2DM and COVID-19 and seems to have a positive effect on inflammation and coagulation." (PMID 36060943, 2022). "Furthermore, acute illnesses, such as COVID-19, may require a higher amount of insulin." (PMID 35246230, 2022). "Recent data have shown that insulin requirements are increased and correlated with high CRP serum levels and COVID-19 severity." (PMID 34124187, 2021). "Specifically for COVID-19, fragments of viral RNA can activate PKR, which will induce IRS-1 serine phosphorylation and consequently insulin resistance." (PMID 33648564, 2021).
COVID-19 (continued). "Notably, early research found that insulin treatment may be associated with adverse outcomes such as death and intensive care unit (ICU) admission; however, evidence regarding the relationship between insulin treatment and COVID-19 remains inadequate and unconvincing." (PMID 34367067, 2021). "On the other hand, COVID-19 can lead to worsening of IR in people with T2DM and T1DM via inducing a pro-inflammatory milieu that can further lead to lowering of insulin sensitivity." (PMID 34728695, 2021). "In COVID-19 patients, the direct interaction with pancreatic β-cells by SARS-CoV-2 leads to a significant reduction in insulin release." (PMID 34124187, 2021). "In one study on eight patients with T2D that were critically ill with COVID-19 and admitted to the ICU, insulin requirements rapidly increased to extremely high doses with a mean peak insulin requirement of 201 units per day (2.2 units/kg/day)." (PMID 34220706, 2021). "Ninety-three in the COVID-19 cohort and 469 in the non-COVID-19 cohort were compared for percentage of blood glucose TIR (70–150 mg/dL) and average daily insulin use." (PMID 33198177, 2020). "For participants without past COVID-19 status, age group 50–59 years compared with 20–29 years increased the prevalence of insulin resistance as measured by TyG." (PMID 40273152, 2025). "The “diagnostic band” at 1743 cm−1, assigned to the aldehyde stretching (vCHO) absorption mode, was increased in the spectra of TZD- and insulin-medicated patients compared with that of MET-medicated patients, confirming that COVID-19 heightens oxidative stress and aldehyde formation effects." (PMID 40650107, 2025). "With HOMA-IR, fasting plasma glucose, insulin and total cholesterol predicted IR in participants without prior COVID-19 status." (PMID 40273152, 2025). "Apart from metformin and insulin analogues, the most common concomitant medications were paracetamol (6 [2.4%] patients), COVID-19 vaccines (4 [1.6%] patients), and nonsteroidal anti-inflammatory medicines (4 [1.6%] patients)." (PMID 39446459, 2025). "COVID-19 subjects might have experienced bed resting and starvation (intensive care unit, ICU), which could have influenced the β cell phenotype, including INS content." (PMID 39232561, 2024). "For clinical data, there was no significant decrease in insulin secretion in the vaccination + COVID-19 model group." (PMID 38609366, 2024). "Similarly, higher mean fasting insulin, proinsulin, C peptide levels, homeostasis model assessment of β-cell function, and HOMA-IR have been found in individuals with COVID-19 compared with healthy controls." (PMID 37934800, 2024). "In patients with COVID-19, however, new-onset DM and severe metabolic consequences of current diabetes, such as diabetic ketoacidosis (DKA) and hyperosmolarity, necessitating extremely high insulin doses, have been reported." (PMID 39304825, 2024). "The beneficial effects of metformin and DPP-4 inhibitors suggest that patients who are established on these antidiabetic agents should remain on their current treatment (i.e., not changed to insulin) if hospitalized for COVID-19." (PMID 39835258, 2024). "This indicates that only PRSs for traits associated with insulin resistance (i.e. obesity, lipodystrophy, and liver/lipid), not insulin production and secretion (i.e. beta-cell and proinsulin), are significantly related to the severity of COVID-19." (PMID 38267566, 2024). "Most patients in the current study knew the common transmission modes of COVID-19, such as respiratory droplets and touching contaminated surfaces; however, only a minority knew that the infection does not spread through insulin injections." (PMID 36767736, 2023). "Notably, two cases exhibited significant complications due to COVID-19 and DKA, necessitating the administration of high doses of intravenous insulin over an extended duration." (PMID 37510181, 2023).
COVID-19 (continued). "The primary objective of this study was to assess if intravenous regular human insulin infusion requirements in patients with diabetic ketoacidosis differed between patients with or without COVID-19." (PMID 36741601, 2023). "In contrast, the majority did not have the knowledge that eating or being in contact with wild animals (n = 139, 55.4%) and using insulin injections (n = 155, 61.8%) do not contribute to the transmission of COVID-19." (PMID 36767736, 2023). "Time on IV RHI infusion was 24.7±69.1 hours versus 14.2±8.9 hours (p=0.65) and the first basal insulin dose was 0.2±0.2 units/kg versus 0.3±0.1 units/kg (p=0.06) between the COVID-19 positive and COVID-19 negative groups, respectively." (PMID 36741601, 2023). "Another recent study confirmed other previous studies that revealed that the insulin/insulin-like growth factor 1 (IGF) signaling pathway, which plays an important role in energy metabolism, is impaired in organs and tissues of severe COVID-19 patients." (PMID 36947108, 2023). "There are situations in which patients have been admitted with severe forms of COVID-19 in both groups, and our study showed the connection between the admission parameters and the treatment without insulin or with insulin at home." (PMID 36983573, 2023). "Insulin requirements after recovery from COVID-19 were not studied if there was a return to baseline." (PMID 38192935, 2023). "The severe form of COVID-19 was found in 66% of all patients (65% in the group without insulin and 67% in the group with insulin)." (PMID 36983573, 2023). "In the critical disease group, favorable outcomes were still more prevalent among COVID-19 patients with oral medication only and oral medication plus insulin but was not statistically significant (83.3%, 60% vs. 25% for critical, p=0.090)." (PMID 35047039, 2022). "They studied 570 COVID-19 patients and classified them as non-diabetic or newly discovered DM according to HbA1c and fasting insulin after exclusion of known DM cases." (PMID 36992767, 2022). "This case highlights the potential increased danger of SGLT2i use in an acute illness, such as COVID-19, even in patients who are not insulin-treated or have already discontinued the medication." (PMID 35718795, 2022). "Postmortem examinations in COVID-19 victims spotted SARS-CoV-2 antigens in pancreatic β-cells, displaying that viral binding to ACE2 in human islets impaired the organ function and reduced the insulin secretion." (PMID 35600601, 2022). "The glucose, insulin and HOMA-IR (p < 0.001), 8-isoprostanes, 3-nitrotyrosine (p < 0.001) and LPO were increased (p = 0.02) while Vitamin D (p = 0.01), H2S, thiols, TAC, GSH and Se (p < 0.001) decreased in COVID-19 patients in comparison to HS." (PMID 35326383, 2022). "The severity of pneumonitis correlates with the insulin requirement, but there does not appear to be a specific effect of COVID-19 on insulin resistance." (PMID 34220705, 2021). "This distinction may be of clinical importance, because it could determine whether normalization of the blood glucose level or the insulin level should be prioritized to reduce ACE2 expression and thus the severity of COVID-19." (PMID 34578858, 2021). "As reported in the literature, an interaction between COVID-19 and glucose-insulin metabolic disorders is postulated in adults and not excluded in pediatrics." (PMID 34067965, 2021). "Also, most of the patients with COVID-19 and T2DM received metformin and insulin therapy as a glucose-lowering regiment during their hospitalization." (PMID 33490288, 2021). "When these types of treatments need to be discontinued due to COVID-19, the alternative choice is insulin, irrespective of the patient setting." (PMID 32456064, 2020). "Subcutaneous insulin therapy was suggested for patients with COVID-19 who had DKA and in whom intravenous insulin infusion was not possible." (PMID 33297431, 2020).